SLC67A1 (solute carrier family 67 member 1)
Description:
May act as a transporter of organic cations based on a proton efflux antiport mechanism. May play a role in the transport of chloroquine and quinidine-related compounds in kidney. Plays a role in the regulation of lipid metabolism (By similarity).
Synonyms: p45-BWR1A; BWR1A; BWSCR1A; HET; IMPT1; ITM; ORCTL2; SLC22A18; SLC22A1L; TSSC5
Tractability: Antibody: UniProt places it where antibodies can reach, with high confidence; its Gene Ontology location is reachable by antibodies, with high confidence; UniProt predicts a signal peptide or a membrane-spanning region; the Human Protein Atlas places it where antibodies can reach. PROTAC: ubiquitination databases record sites on it.
Target class: SLC superfamily of solute carriers; Electrochemical transporter; SLC22 family of organic cation and anion transporters; Transporter
Gene: Protein-coding gene on chromosome 11 (2,899,718 to 2,925,247, forward strand). Ensembl gene ENSG00000110628.
Subcellular location: Apical cell membrane
Subcellular location (Human Protein Atlas): Plasma membrane
Pathways (Reactome):
Disease: Defective SLC22A18 causes lung cancer (LNCR) and embryonal rhabdomyosarcoma 1 (RMSE1)
Transport of small molecules: SLC-mediated transport of organic cations
Gene Ontology:
Molecular function: protein binding; ubiquitin protein ligase binding; xenobiotic transmembrane transporter activity; transmembrane transporter activity
Biological process: xenobiotic detoxification by transmembrane export across the plasma membrane; xenobiotic transport; amine transport; transmembrane transport
Cellular component: apical plasma membrane; cytoplasm; membrane; nuclear envelope; plasma membrane
Genetic constraint (gnomAD): Loss-of-function variants: 32 observed, 31.56 expected, observed/expected ratio (o/e) 1.01, 90% interval 0.76 to 1.36. The upper end of that interval is the gene's LOEUF score, 1.36, which puts it in group 5 of 6, group 1 being the genes least tolerant of losing a copy. Missense variants: 598 observed, 551.85 expected, observed/expected ratio (o/e) 1.08, 90% interval 1.01 to 1.16. Synonymous variants: 285 observed, 257.05 expected, observed/expected ratio (o/e) 1.11, 90% interval 1.01 to 1.22.
Homologues: Orthologues: chimpanzee SLC22A18 (99% identical), macaque SLC22A18 (92% identical), pig SLC67A1 (77% identical), guinea pig SLC67A1 (76% identical), mouse Slc22a18 (76% identical), dog SLC67A1 (76% identical), rat Slc22a18 (75% identical), tropical clawed frog slc22a18 (50% identical), zebrafish slc22a18 (50% identical), Caenorhabditis elegans C53B4.3 (25% identical).
Diseases named in the same sentence as SLC67A1 in open-access papers:
SLC67A1 is named in the same sentence as 38 diseases in open-access papers, as found by Europe PMC text mining. Sharing a sentence is not in itself a finding about the gene and the disease.
SLC67A1 shares sentences with these, for which no sentence is quoted: tumor (21 papers); glioma (11); cancer (10); breast carcinoma (5); Wilms tumor (5); colorectal cancer (4); lung carcinoma (4); non-small cell lung carcinoma (3); alcohol dependence (2); COVID-19 (2); glioblastoma (2); Globozoospermia (2); hepatoblastoma (2); lung adenocarcinoma (2); prostate carcinoma (2); adenocarcinoma (1); Allergy (1); Barrett esophagus (1); colon adenocarcinoma (1); colon cancer (1); colorectal tumors (1); dysplasia (1); embryonal rhabdomyosarcoma 1 (1); hepatocellular carcinoma (1); infection (1); insulinoma (1); leukemia (1); melanoma (1); metastatic melanoma (1); Obesity (1).
A further 8 diseases each share a sentence with SLC67A1 in 1 paper.